PRL (prolactin)
Diseases named in the same sentence as PRL in open-access papers (continued):
Sharing a sentence is not in itself a finding about the gene and the disease.
cancer (continued). "Prolactin (PRL) has been implicated in the development of different types of cancer." (PMID 26346346, 2015). "Overall, a correlation was established between the high late-pregnancy levels of PRL and increased cancer EMT and stemness via in vitro and in silico experimentation." (PMID 41501898, 2026). "There have also been several studies which link elevated PRL levels with cancer progression and increasing cancer stage." (PMID 41501898, 2026). "The expressions of CD44 and CD133 were tested to evaluate increases in cancer cell stemness after each of the PRL treatments at 12, 24, and 48 h." (PMID 41501898, 2026). "An increase in EMT and CD44, the cancer stem cell marker, with pregnancy levels of PRL dose, was also confirmed." (PMID 41501898, 2026). "While these results are promising, more work needs to be done to confirm that liposomal TRAIL can provide a more effective and safe treatment option against metastasizing cancer cells that have been exposed to pregnancy levels of prolactin." (PMID 41501898, 2026). "The first factor of interest is the link between increased prolactin signaling during pregnancy leading to increased cancer cell aggressiveness." (PMID 41501898, 2026). "Combining analysis of GO and KEGG enrichment found that these genes were mainly related to proteoglycans in cancer, the prolactin signaling pathway, EGFR tyrosine kinase inhibitor resistance, and the Rap1 signaling pathway." (PMID 40427433, 2025). "CNNM2 is thought to promote cell replication and enhance migration and invasion of cancer cells through the formation of PRL-CNNM complexes." (PMID 41174507, 2025). "We included the protein biomarkers, HE4, CA19-9, CEA, and AFP, which are all commonly used in clinical cancer detection, as well as prolactin (PRL) and interleukin-6 (IL-6), which have been reported in previous studies." (PMID 40502685, 2025). "Other relevant pathways included central metabolic pathways, prolactin signaling, and microRNAs involved in cancer, underscoring the regulatory role of the selected targets in tumorigenesis and cancer cell survival." (PMID 41150809, 2025). "Prolactin (PRL) promotes cell proliferation, and PRL receptor expression is elevated in various cancer types." (PMID 40478803, 2025). "The results show that the antioxidant targets of KGEA were related to multiple pathways among proteoglycans in cancer, prolactin signaling pathway, and EGFR tyrosine kinase inhibitor resistance, and that KGEA mainly regulated these pathways to exert function." (PMID 40427433, 2025). "Pro-inflammatory mediators such as eicosanoids and prolactin, alongside other inflammatory agents, play considerable effects in cancer promotion driven by these factors." (PMID 40420174, 2025). "KEGG analysis results show that the targets of the 6 molecules in the treatment of AD are significantly enriched in the Prolactin signaling pathway, Pathways in cancer, neuroactive ligand-receptor interaction, and L-17 signaling pathway." (PMID 40355181, 2025). "The pathways ranked top 20 of KEGG were screened out, and that mainly related to proteoglycans in cancer, prolactin signaling pathway and EGFR tyrosine kinase inhibitor resistance." (PMID 40427433, 2025). "Phosphatases of regenerating liver (PRL or PTP4A) are protein phosphatases implicated in cell growth, magnesium homeostasis, and cancer metastasis." (PMID 40398601, 2025). "PRL, frequently overexpressed in cancers, acts as a pseudo phosphatase by binding to CNNM4, modulating magnesium homeostasis." (PMID 39691602, 2024). "To correlate the CD44 expression to iron uptake, we used an antibody to block CD44 and examined the iron uptake in cancer cells following prolactin treatment." (PMID 39201626, 2024). "It contained several signalling pathways related to cancer, such as Ras-, Foxo-, Prolactin-, C-type lectin receptor-signalling pathway, etc., among which, the Ras signalling pathway was the most important." (PMID 39224778, 2024).
cancer (continued). "CD44 plays an important role in the prolactin-driven accumulation of labile iron pools inside cancer cells." (PMID 39201626, 2024). "Although the activation of PRLR pathway has been identified as a cancer promoter, targeting PRL-PRLR axis alone achieves limited effects in clinical trials." (PMID 38898487, 2024). "KEGG enrichment analysis showed that 125 signaling pathways were mainly enriched in the chemical carcinogenesis-receptor activation pathways in cancer, the prolactin signaling pathway, the PI3K-AKT signaling pathway, and endocrine resistance." (PMID 39062817, 2024). "The dark side of prolactin in promoting cancer progression has been well documented in multiple cancers." (PMID 39201626, 2024). "PRL plays a significant role in certain cancers, including OV, and the co-expression of PRL with CNNM inhibits CNNM-mediated Mg2+ efflux, affecting intracellular magnesium levels linked to cancer progression." (PMID 39691602, 2024). "Collectively, these data show that CD44 is involved in prolactin mediated iron uptake in cancer cells." (PMID 39201626, 2024). "This study marks the first exploration of prolactin’s novel role in mediating iron distribution between two distinct cell types: cancer cells and macrophages." (PMID 39201626, 2024). "Stimulation by prolactin enhances iron accumulation in cancer cells but induces iron release from macrophages." (PMID 39201626, 2024). "(b) Tamoxifen was given as monotherapy for 10 months after discontinuing DA in one patient with prolactin-secreting cancer." (PMID 36950000, 2023). "We found that choline metabolism in cancer, bile secretion, prolactin signaling pathway, pyrimidine metabolism, 2-carboxylic acid metabolism, and various amino acid metabolism pathways are significantly enriched in both positive and negative ion modes." (PMID 36675052, 2023). "The mechanism of action of prolactin in stimulating the processes of cancer metastasis is quite complex and includes endocrine, paracrine, and autocrine mechanisms, including interactions with immune cells." (PMID 38201606, 2023). "The presence of metastasis depends on many factors, including the molecular profile of cancer (according to the TCGA—Genome Atlas), the activity of certain hormones (estrogen, prolactin), and pro-inflammatory adipocytokines." (PMID 38201606, 2023). "Sex hormones with known roles in cancer include prolactin (PRL), luteinizing hormone (LH), follicle-stimulating hormone (FSH), gonadotropin-releasing hormone (GNRH), estrogen (E2), progesterone (P) and testosterone (T)." (PMID 37370722, 2023). "These metabolites were mainly enriched in “prolactin signaling pathway”, “steroid hormone biosynthesis”, “aldosterone synthesis and secretion”, and “pathways in cancer”." (PMID 37158919, 2023). "In our own studies, we sought to identify novel targets involved in pancreatic ductal adenocarcinoma (PDAC) progression, and came across a pilot clinical trial that studied serum prolactin levels in women with different cancers." (PMID 36714582, 2022). "High expression of PRLR and circulating PRL can drive the expression of genes involved in proliferation, migration, and invasion of cancer cells." (PMID 36714582, 2022). "Together, these reports paint a more nuanced picture of PRL action in established cancers, and potential for very different outcomes depending on context." (PMID 35784527, 2022). "A negative correlation between the total cholesterol and high-density lipoprotein and prolactin was particularly prominent in cancer cases." (PMID 35323711, 2022). "In KEGG, the major pathway was indicated as EGFR tyrosine inhibitor resistance, prolactin signaling pathway, and pathway in cancer." (PMID 36531045, 2022).
cancer (continued). "Increasing evidence suggests the stimulatory effects of PRL on several cancers, such as lymphoid, mammary, colon, hepatocellular, prostate, ovarian, and endometrial carcinomas." (PMID 35820883, 2022). "With age, nulliparous females spontaneously develop histologically diverse, metastatic ER+ carcinomas with long latencies, mirroring the epidemiologic link between PRL exposure and aggressive ER+ cancer." (PMID 35784527, 2022). "In cancer cells, constitutive prolactin activity promotes cell proliferation, cell motility, angiogenesis, and metastasis." (PMID 36619589, 2022). "The efficacy of these preclinical studies demonstrates the validity of targeting PRLR while also establishing the critical role of PRL : PRLR signaling in human cancers." (PMID 36714582, 2022). "Transgenic PRL not only enhanced carcinogenesis, but also markedly influenced the resulting cancers in ways that would impact treatment responses." (PMID 35784527, 2022). "All those targets involved in the signal transduction of the prolactin signaling pathway, central carbon metabolism in cancer, EGFR tyrosine kinase inhibitor resistance, endocrine resistance, and VEGF signaling pathway." (PMID 36408342, 2022). "KEGG enrichment analysis revealed that the interacting partners of PIK3R3 are involved in the ErbB signaling pathway, proteoglycans in cancer, FoxO, prolactin, chemokine, and insulin signaling pathways." (PMID 35761259, 2022). "Another mechanism important for PRL to support tumorigenesis is by inhibiting apoptosis of cancer cells." (PMID 34745013, 2021). "Similar results were obtained by the same group in PRL- responsive human prostate DU-145 cancer cells in which the PRL-induced cell growth was potently inhibited by both AEA and 2-AG." (PMID 33478092, 2021). "Because many components, including PRL, surround the microenvironment, it is interesting to understand the hormone’s modulation in cancer cells." (PMID 34745013, 2021). "A pathway analysis of all 630 gene targets showed four enriched KEGG pathways: proteoglycans in cancer, rennin secretion, melanogenesis, and prolactin signaling pathway." (PMID 34186489, 2021). "According to previous studies, the concept of locally produced PRL, which can activate its receptor on target cells, has emerged as a new mechanism in chronic inflammatory diseases and several hormone sensitive cancer models." (PMID 34358244, 2021). "The KEGG pathway of upregulated DEGs was mainly enriched in infections, prolactin, and cancer related pathways." (PMID 34037315, 2021). "Although best known for its role in lactation, prolactin is also known to promote the development and progression of breast and other cancers." (PMID 34375938, 2021). "The STAT3/5 regulation by PRL observed in this study supports previous studies showing activation of these transcription factors in different types of cancer cells and the effect is cell-dependent." (PMID 34358244, 2021). "CAPTEM treatment followed by TMZ monotherapy (TMZ resistant cases) has been reported in eight cases (three ACTH secreting carcinomas, two PRL secreting carcinomas, one null-cell carcinoma, and two cases not stated)." (PMID 33841328, 2021). "Findings of increased PRLR levels in tumors combined with a frequently observed elevation of serum PRL in cancer patients formed the basis for a clinical trial to suppress serum PRL with dopamine receptor agonists." (PMID 32121009, 2020). "Another soluble factor increased in HCT-116, prolactin is actively involved in tumorigenesis in several cancers." (PMID 31742371, 2020). "PRL has been shown to promote the proliferation and differentiation of various types of cancer cells 16,25." (PMID 33173437, 2020).
cancer (continued). "The pathway analysis exhibited the potential signal pathways of miR-203 involved in CRC including pathways in cancer, wnt pathway, prolactin signaling pathway, proteoglycans in cancer, FoxO pathway, focal adhesion and Ras pathway." (PMID 33059609, 2020). "First, the vast majority of reported PCs are endocrinologically active, including ACTH-, and PRL-secreting carcinomas, which are the most common." (PMID 33643220, 2020). "Seven of these biomarkers (TNFα, sFasL, SCF, VEGF, leptin, prolactin, OPN) were also significantly elevated in the cancer-associated cluster compared to the high diversity/inflammation cluster (P ranging from 0.02 to <0.0001)." (PMID 31089160, 2019). "There is strong evidence that increased levels of prolactin or its receptor can promote cancer formation." (PMID 31581718, 2019). "The physiological relationship between estrogen and prolactin has been well demonstrated; however, the impact of this relationship on cancer has been little explored." (PMID 31507337, 2019). "The combination of PRL, CEA, and CYFRA21 yielded a better optimal diagnostic efficacy for cancer patients (AUC = 0.960, 95% CI: 0.921–0.999) than the individual biomarker alone." (PMID 30555348, 2018). "We find the combination which contains TTR and Prolactin gives high performance for cancer detection." (PMID 30396341, 2018). "Large prospective epidemiologic studies have linked the hormone, prolactin (PRL), to increased risk of development of aggressive ERα + cancers, and smaller-scale studies also suggest that it contributes to their progression." (PMID 28103936, 2017). "There are many publications supporting roles for prolactin in the progression of a variety of cancers." (PMID 28422740, 2017). "Thienopyridone has been shown to selectively inhibit PRL activity compare with other PTPs and also had an antiproliferative effect in cancer cells." (PMID 26969161, 2016). "The long form of the human Prolactin Receptor (PRLR) of 622 amino acids with extended cytoplasmic domain present in the cell membrane of normal and cancer cells mediates all the known diverse functions of prolactin (PRL)." (PMID 27564112, 2016). "We would predict heightened cooperation between PRL and growth factors through these localized signaling platforms in rigid environments in aggressive luminal B cancers, which also respond strongly to growth factors." (PMID 27344177, 2016). "In particular, this review refers to the roles of prolactin (PRL) signaling that contribute to normal mammary gland function, which are subverted in cancer to contribute to the disease process." (PMID 27782069, 2016). "Recently, there are several studies that involve PRL in the development of different types of cancer such as breast, prostate, ovarian and cervical." (PMID 26346346, 2015). "In other studies, increased levels of estrogens, progesterone and prolactin were found in serum and/or tissue homogenates of dogs with malignant neoplasms." (PMID 26370564, 2015). "The abnormal induction of PRL/PRLR has been associated with the development and progression of various types of cancers such as breast, prostate, colorectal, larynx, and hepatocellular." (PMID 26346346, 2015). "To date, several reports associate the expression of the PRL/PRLR with the development and progression of cancers such as breast, prostate, colorectal, gynecological, laryngeal, and hepatocellular." (PMID 24148306, 2013). "The altered expression of prolactin (PRL) and its receptor (PRLR) has been implicated in breast and other types of cancer." (PMID 24148306, 2013). "A prospective study already in progress will show if female dogs affected by malignant tumors in fact have increased PRL levels in addition to decreased tumorous PRLR expression." (PMID 22647582, 2012). "Among patients with PRL- or ACTH-producing carcinomas, TMZ was shown to be effective in about three-fourths." (PMID 23091742, 2012).
cancer (continued). "The influence of human prolactin (hPRL) on the development of breast and other types of cancer is well established." (PMID 21505459, 2011). "Prolactin-induced carcinomas were markedly diverse with respect to histotype, ERα/PR expression, and activated signaling cascades." (PMID 21276249, 2011). "Our studies demonstrate that elevated local PRL can promote diverse carcinomas, which display varying levels of ERα/PR, nuclear pStat5, pERK1/2 and pAKT, and AP-1 components." (PMID 21276249, 2011). "Using a subtractive hybridisation approach, we identified a number of cancer-related genes whose expression is modified by the addition of prolactin in the human breast adenocarcinoma cell line, SKBR3." (PMID 19014541, 2008). "The prolactin-mediated induction of HSP90α implicates prolactin in the acquisition or maintenance of each of those cancer-related traits." (PMID 19014541, 2008). "At the same time, the JAK/STAT pathway interacts with other significantly enriched cancer-related pathways, such as the prolactin signaling pathway, suggesting that it may act as a key regulatory hub." (PMID 40351419, 2025). "In vitro studies have investigated the potential effects of PRL on various cancer cell types." (PMID 40478803, 2025). "Also, there was a lack of data from the patient’s medical history about immunohistochemistry for PRL of removed OC tissue, PRL levels onset of the cancer diagnosis, and its changes over the course of the disease." (PMID 39928792, 2025). "Both HCMV and PRL may utilize similar immunological pathways, contributing to an inflammatory environment that supports viral activity and impacts cancer progression." (PMID 41476991, 2025). "Moreover, the relationship between sleep disturbances and cancer progression is further explained through the lens of various hormones such as growth hormones, prolactin, dopamine, estrogen, leptin, and ghrelin." (PMID 39980544, 2025). "Despite the challenges posed by competitive doping in the functionalization process, the heterobifunctional nature of PBASE facilitates the detection of a diverse range of biomarkers, including prolactin (PRL) hormone antibodies—a molecule which is involved in reproduction, metabolism, and cancer." (PMID 41368593, 2025). "Notably, several metabolites involved in this pathway also participate in other signaling cascades, including Pathways in cancer, Ovarian steroidogenesis, and Prolactin signaling, which were likewise downregulated." (PMID 41009664, 2025). "Besides its function in reproduction and lactation, prolactin (PRL) affects metabolic processes, cancer, and the immune system." (PMID 40362476, 2025). "ARS and its derivatives may treat AD by modulating pathways such as Prolactin signaling, cancer pathways, neuroactive ligand-receptor interaction, and IL-17 signaling." (PMID 40355181, 2025). "Pathway enrichment analysis using KEGG indicated significant enrichment (p < 0.05) pathways, including prolactin signaling, oxytocin signaling, GnRH signaling, and central carbon metabolism in cancer, distinguishing metabolic profiles between high and low prolificacy groups." (PMID 39857368, 2024). "In addition, prolactin, together with leptin, osteopontin, and insulin-like growth factor 2, provides high sensitivity and specificity for early-stage cancer prediction." (PMID 39201626, 2024). "Prolactin treatment upregulated FPN I in both cancer cell lines (EO771 and Py230)." (PMID 39201626, 2024). "Given the growing evidence of PRL involvement in various cancer types, we first assessed if they could be potential targets for drug therapy in GBM." (PMID 38904264, 2024). "Common targeted genes were mostly involved in pathways in tumorigenesis, HIF-1 signaling pathway, PD-L1 expression and PD-1 checkpoint pathway in cancer, FoxO signaling pathway, prolactin signaling pathway, proteoglycans in cancer, and relaxin signaling pathway." (PMID 39101145, 2024).